TXN (thioredoxin)
Diseases named in the same sentence as TXN in open-access papers (continued):
Sharing a sentence is not in itself a finding about the gene and the disease.
cancer (continued). "This chemical reaction could be accomplished by the thioredoxin system, which is overexpressed in cancer cells and reduces the disulfide bonds of proteins and peptides." (PMID 39274973, 2024). "In certain types of cancer, the antioxidant function of glutathione may become unnecessary due to the thioredoxin antioxidant pathway fulfilling the antioxidant requirements." (PMID 38256132, 2024). "Our analysis led to the identification of PIK3R1, CCND1, TERF2IP, SLC25A4, CAPN2, and TXN as hub genes, which could potentially serve as targets for interventions in both MN and cancer." (PMID 38846934, 2024). "Given the critical role of the thioredoxin system in these diseases, we speculate that TRXR1-specific inhibitors, by affecting the thioredoxin system and thus disulfide bonds, may also be applicable to cancer, cardiovascular diseases and CNS diseases." (PMID 38685115, 2024). "Additionally, the regulator of the redox signaling pathways thioredoxin (TXN) system has emerged as an important regulator of cancer development." (PMID 38732105, 2024). "Consequently, TXN inhibitors remain both promising and complex as potential candidates in the fight against cancer." (PMID 39090114, 2024). "Similarly, another antioxidant protein thioredoxin showed upregulated expression in androgen‐independent PCa and its inhibition led to decrease in cancer growth." (PMID 38400579, 2024). "PRDX6 (peroxiredoxin 6) and TXN (thioredoxin) are known for their antioxidant activities, and TXN enhances NK cell-derived anti-cancer immunity in the tumor microenvironment (TME), suggesting a potential for their inductions to contribute to taxifolin’s antioxidant actions." (PMID 37835514, 2023). "The thioredoxin (Trx) system is a key cellular antioxidant pathway important in defence against oxidative stress and plays an important role in regulating therapeutic response of cancer cells." (PMID 35344158, 2022). "An increase of the thioredoxin reductase/thioredoxin (TrxR/Trx) system has been reported in many tumors compared to normal tissues and the ability of certain cancer cells to maintain a highly reduced intracellular environment is correlated with tumor aggressiveness and drug resistance." (PMID 34850406, 2022). "In this context, inhibition of TXN using ferroptocide has been shown to induce ferroptosis in several cancer cells, indicating that TXN might be a bone fide pan-cancer dependency protecting from ferroptosis." (PMID 35912247, 2022). "TXNRD1, the cytosolic selenoprotein thioredoxin reductase 1 (TrxR1), served as a central regulator of the thioredoxin system and may be inhibited pharmacologically to achieve selective killing of cancer cells." (PMID 36524129, 2022). "Besides, glutathione and thioredoxin antioxidant pathways synergize to drive cancer initiation and progression." (PMID 35821802, 2022). "In addition, thioredoxin expression was upregulated in ten of thirteen human carcinoma samples based on bulk sequencing available through The Cancer Genome Atlas (TCGA), as compared to healthy tissue." (PMID 35250998, 2022). "Accordingly, targeting the thioredoxin system is an effective way to eradicate cancer cells without causing other collateral damage to surrounding normal cells." (PMID 34485384, 2021). "The literature exclusively reports that knockout or knockdown of a redoxin, either a peroxiredoxin or a thioredoxin, inhibits cancer cell proliferation and that overexpression protects against various types of cellular stressors and promotes cancer cell growth or drug resistance." (PMID 33805811, 2021). "The carbonylated thioredoxin remains associated with the active site of the N-terminus of ASK1, thus inhibiting the kinase and blocking the induction of the apoptosis process dependent on ASK1, thus leading to cancer progression." (PMID 34302052, 2021).
cancer (continued). "Therefore, cancer cells rely heavily on antioxidants including the thioredoxin system to maintain redox homeostasis to survive." (PMID 34485384, 2021). "The thioredoxin system plays key roles in regulating cancer cell malignancy." (PMID 33846376, 2021). "Thioredoxin is a growth factor that is overexpressed in many aggressive forms of cancer." (PMID 33072014, 2020). "Overexpression of glutaredoxin and thioredoxin in cancer cells may further perturb the mechanisms limiting production of ROS by OGDHC in normal cells." (PMID 32466567, 2020). "Thioredoxin‐thioredoxin reductase system plays a key role in development of cancer cells." (PMID 33289312, 2020). "Cancers with NRF2 hyperactivating mutations share a set of upregulated target genes, including key regulators involved in the thioredoxin and glutathione system, metabolic enzymes, transporters, and others, enabling a cancer growth advantage and consequently a worse overall survival." (PMID 33228209, 2020). "On the other side, it has been found that thioredoxin is involved in the growth of cancer cells." (PMID 33289312, 2020). "Various classes of therapeutic pro-oxidants (e.g., organic endoperoxides and Michael-type electrophiles, antagonists of glutathione and thioredoxin metabolism, MnSOD-mimetics, Nrf2 antagonists, and inducers of ferroptosis) have been examined as promising experimental cancer therapeutics." (PMID 31035569, 2019). "Indeed, GSH and thioredoxin, both decreasing levels of ROS below the ones that would lead to apoptosis, are implicated in different stages of carcinogenesis: GSH in cancer initiation and thioredoxin in the progression of already-established cancer." (PMID 31366062, 2019). "Under the high oxidative stress (treatment with 500μM H2O2), cancer cell viability was reduced by 90% upon silencing of either HMOX1 or TXN, indicating that both antioxidant defense mechanisms have to be intact for cancer cell survival in high oxidative stress conditions." (PMID 29755668, 2018). "Recently, multiple reports have indicated that targeting the thioredoxin system with various drugs could be an efficient strategy for killing chemoresistant cancer cells." (PMID 29755668, 2018). "Therefore, the mitochondrial thioredoxin system actually protects cancer cell propagation and contributes to chemoresistance." (PMID 29891764, 2018). "Interestingly, the Tg(act-TXN)+/0 mice showed reduced levels of Trx1 overexpression with age and a slightly higher incidence of cancer compared to WT mice." (PMID 30370017, 2018). "We also observed that expression levels of rate-limiting enzymes involved in the synthesis of other anti-oxidation factors are up-regulated in eight types of cancer, suggesting other anti-oxidation factors, such as catalase and thioredoxin, are also used to protect cancers from high levels of ROS." (PMID 29116024, 2017). "The thioredoxin system has emerged as an important target in cancer chemotherapy, because both Trx1 and TrxR1 have been shown to be overexpressed in a variety of human cancer types and associated with increased tumor growth, drug resistance and poor patient prognosis." (PMID 26919110, 2016). "Indeed, combined inhibition of glutathione and thioredoxin systems synergizes to kill cancer cells 11, suggesting the existence of mutually compensatory mechanisms." (PMID 27485632, 2016). "Whether blockade of glutathione and thioredoxin is useful in eliminating cancer stem cells remain unknown." (PMID 27485632, 2016).
cancer (continued). "As a component of the thioredoxin system, TrxR1 has been evidenced to be over-expressed and constitutively active in various kinds of cancer cells, enhance cancer cells proliferation, and exhibit pro-survival signaling which attributes to inciting a pro-survival effect in cancer cells." (PMID 26919094, 2016). "Combining with the role of EMT in chemoresistance and cancer cell invasion/metastasis, our data suggest that TXN may play a crucial role in regulation of SACC metastasis through EMT." (PMID 26325518, 2015). "Thioredoxin is involved in various biological activities, including regulating cancer cell growth." (PMID 25871387, 2015). "The GSH and thioredoxin systems are generally activated in cancer." (PMID 25221514, 2014). "Eukaryotic thioredoxin may be a secreted growth factor or a chemokine for immune cells, which implies potential applications in cancer therapy." (PMID 23372719, 2013). "We investigated the possibility that the thioredoxin system protects against TNF-α-induced cancer cell death by examining whether TR1/Trx1 status controls TNF-α-induced apoptosis in EMT6 murine breast cancer cells." (PMID 24039713, 2013). "Gene-set enrichment, gene ontology, network, and pathway analyses revealed that members of the thioredoxin and glutathione pathways are prominent components of this oncogenic signature and that activation of these pathways is common feature of many cancer entities." (PMID 24342878, 2013). "The thioredoxin system is an important molecular target for anti-cancer therapy." (PMID 24039713, 2013). "Studies have shown that the thioredoxin system can predict prognosis of other types of cancer." (PMID 22615972, 2012). "The thioredoxin redox system has been suggested recently as a therapeutic target for cancer therapy, based on the observation that thioredoxin is overexpressed in many aggressive tumors and that siRNA-mediated knockdown of TXNRD1 decreased tumor progression and metastasis in mice." (PMID 20584310, 2010). "Thioredoxin is a small redox-regulating protein, which plays crucial roles in maintaining cellular redox homeostasis and cell survival and is highly expressed in many cancers." (PMID 24281068, 2010). "However, only a few studies exist that investigate the regulation of thioredoxin in the hypoxic and cycling hypoxic response in cancers." (PMID 24281068, 2010). "Indeed, some compounds such as the SAHA histone deacetylase inhibitor can target the thioredoxin system leading to ROS generation and induction of apoptosis in cancer cells." (PMID 19903329, 2009). "Hence, it is a key target for the development of drugs to treat cancer, especially since increased thioredoxin levels are seen in many human primary cancers." (PMID 18455736, 2008). "Therefore, cancer cells may upregulate thioredoxin system to maintain moderate level of ROS and tumor phenotypes, while also rendering cancer cells vulnerable to oxidative stress." (PMID 40914135, 2025). "Therefore, targeting cancer vulnerability by inhibiting either the thioredoxin or glutaredoxin system could pave a way to more cancer-specific therapies." (PMID 32727562, 2020). "Thus, such known features of cancer cells as increased glutathione and the up-regulated thiol-disulfide reductases thioredoxin and glutaredoxin, may promote the ROS production by OGDHC, requiring decreased levels of holo-OGDHC in cancer vs normal cells." (PMID 32466567, 2020).
cancer (continued). "Taken altogether, the results from this and other studies demonstrate that thioredoxin overexpression might represent a signature in cancer, and that over-activated thioredoxin signaling might be a prognostic marker in cancer, and might also serve as potential therapeutic targets in cancer therapy." (PMID 30382079, 2018). "Therefore, the suppression of the ASK1 pathway may be promoting cancer development, which resulted in the accelerated mortality in old Tg(TXN)+/0 mice." (PMID 30370017, 2018). "However, the mechanistic basis by which the thioredoxin system inhibition suppresses cancer progression remains unclear." (PMID 24039713, 2013). "When we test the effects of reduced levels of thioredoxin in cytosol or mitochondria on aging, we may observe the reverse effects, that is, life-extension and reduction of cancer in the Trx1KO mice, while the Trx2KO mice showed little effects on lifespan but showed impaired mitochondrial function." (PMID 24764510, 2012). "Several reports have demonstrated that increases in TXN and TXNRD1 under glucose deprivation conditions support cancer cell survival and migration 62, 63, whereas enhanced stability of TXNIP mRNA inhibits tumor metastasis and glycolysis." (PMID 39744566, 2025). "Antioxidant systems like glutathione S transferase (GST) and thioredoxin (Trx) neutralize excessive ROS and RNS but nonetheless, persistent oxidative stress still contributes to aging and cancer." (PMID 40559842, 2025). "We first evaluated the expression of TXN, TXNRD1, and TXNIP in pan-cancer data from TCGA and GTEx to further investigate the connection between the Trx system and malignancies." (PMID 39744566, 2025). "Reductases such as TXN‐1 and TXN‐2, found in the cytosol and mitochondria, respectively, also play an important role in governing the redox balance in different types of cancer cells." (PMID 40377005, 2025). "Se nanoparticles also decreased cancer cell viability and proliferation while increasing the mRNA expression of TXN, GPX1, GPX2, GPX3, and GPX4 in many of the cancer cell lines." (PMID 39408290, 2024). "Specifically, targeting key antioxidant proteins, such as SLC7A11, GCLC, GPX4, TXN, and TXNRD, represents an emerging approach for inducing oxidative cell death in cancer cells." (PMID 39090114, 2024). "Later in cancer development, other antioxidant pathways, such as the thioredoxin antioxidant pathway (TXN), can take over the role of continuing to develop the cancer." (PMID 38921002, 2024). "Consistent with this notion, the mouse homologous genes of human PRDX6, MAGOHB, NUCKS1, DCAF13, and TXN were upregulated by taxifolin in LL2 LC tumors and facilitated CTL-derived toxicity towards cancer cells." (PMID 37835514, 2023). "An adjusted (Tukey) box-plot analyses showed evidence of lower concentrations of SPRR1B, CRNN, TXN and FABP5 in cancers compared to controls." (PMID 36807337, 2023). "In some malignant tumors, the TXN-dependent system is often activated, and the simultaneous inhibition of both GSH and TXN pathways is an effective method for inducing cell death." (PMID 38139836, 2023). "S100A8 markedly induced expression of several redox genes on Day 10, including superoxide dismutase (SOD1) (5.8 x 105 fold, p < 0.01) and thioredoxin (TXN) (1.5 x 105 fold, p < 0.05) in lungs of mice with LLC cancers." (PMID 35655772, 2022). "Despite limited evidence, these findings intimate that TXNRD2 and TXNRD3 also inhibit oxidative stress via the thioredoxin system in cancers as TXNRD1, thereby promoting cancer cell resistance to cell death." (PMID 36358931, 2022). "The action of resveratrol led to the sensitization of cancer cells to the action of chemotherapeutic agents by influencing the expression of genes (ABCB1, ANXA1, TXN) and proteins (P-gp, annexin I, thioredoxin) related to the MDR process." (PMID 34299624, 2021).
cancer (continued). "Suppression of the expression level of Nrf2 via applying a CRISPR/Cas9 genome editing system illustrated that ERBB3 and IGF1R signaling pathway accompanied by thioredoxin and peroxiredoxin proteins play an effective role in KEAP1-mutant cancer cells." (PMID 33768092, 2021). "Therefore, to evade ROS-induced cell death, cancer cells have an aberrant metabolism that promotes some agents to scavenge ROS and repair ROS-induced damage with molecules like glutathione peroxidase, glutathione-S-transferase, glutaredoxin, thioredoxin, superoxide dismutase, and catalase." (PMID 33959633, 2021). "Annexin A1 (ANXA1) and thioredoxin (TXN) are other possible mechanisms involved in MDR and consequently, cancer progression." (PMID 33478512, 2021). "Inhibition of prooxidative enzyme activation, including the GSH, thioredoxin (TXN), or NADPH oxidase, can represent a potential target in cancer prevention and treatment." (PMID 32547652, 2020). "One notable example is the known thioredoxin inhibitor Vorinostat (Zolinza), which inhibits HIF1-α and is approved for cancer treatment." (PMID 32605023, 2020). "In fact, drugs targeting the thioredoxin and glutathione system (Trx, TrxR and GSH) have been identified as promising targets for cancer therapy, especially in combination with radiotherapy." (PMID 33202866, 2020). "The overexpression of TXN and TXNRD improved the survival of cancer cells as it decreases apoptosis and enhances its tolerance to oxidative stress." (PMID 32679649, 2020). "Mechanistically it was found in prostate (LNCaP), breast (MCF7), and bladder (T24) cancer cell lines that both vorinostat and entinostat induce ROS by inhibiting the binding protein-2 (TBP-2), an inhibitor of the cellular thioredoxin (Trx)." (PMID 31248188, 2019). "Moreover, thioredoxin stimulates proliferation of normal and tumor cells, and is present in high concentrations in tumor cells, so an impairment of the TrxR activity may be involved in some forms of cancer." (PMID 29371830, 2018). "Among the up-regulated genes, we observe the proto-oncogene FOS62 as well as a set of other cancer-related genes such as HSPE1, TXN and TXNIP." (PMID 29434270, 2018). "Another antioxidant pathway, the thioredoxin pathway, was recently shown to play an important role in cancer cells, rendering GSH dispensable during cancer progression." (PMID 27542228, 2016). "This review focuses on how thioredoxin-1 (TXN1), thioredoxin reductase-1 (TXNRD1), and members of the protein disulfide isomerase (PDI) family regulate thiol-disulfide balance at the cancer cell surface and how these alterations can be exploited for theranostic applications." (PMID 41903319, 2026). "Crucially, cancer cells can adapt to elevated ROS levels by increasing the activity of endogenous antioxidant systems, such as glutathione (GSH), superoxide dismutase (SOD), catalase (CAT), and the thioredoxin (Trx) system." (PMID 41011117, 2025). "Similarly, in pancreatic cancer, the thioredoxin system, of which TXNRD1 is a key component, enables cancer cells to evade oxidative stress-induced cell death." (PMID 41333220, 2025). "The results of our study suggest that the Trx system, which consists of TXN, TXNRD1, and TXNIP, may be useful for the early diagnosis and monitoring of cancer." (PMID 39744566, 2025). "Both PX-12 and Gambogic acid have been used in cancer research as inhibitors of TXN, but the effects of Gambogenic acid and Biotiny lated gambogic acid on TXN have not been reported." (PMID 40108736, 2025). "Some cellular defensive proteins, such as catalase, superoxide dismutase (SOD), thioredoxin (TRX), and nuclear factor erythroid 2–related factor 2 [NRF-2, a regulator in cellular antioxidant activity], can overcome oxidative stress in cancer cells." (PMID 38666017, 2024).